LEP (leptin)
Diseases named in the same sentence as LEP in open-access papers (continued):
Sharing a sentence is not in itself a finding about the gene and the disease.
Obesity (continued). "Several mouse models of obesity exist, and we chose the most commonly used and well characterized, ob/ob mice, homozygous for a mutation in the leptin gene." (PMID 39456952, 2024). "High levels of leptin in obesity are associated with cardiac and renal fibrosis, increased aldosterone production, and sodium retention." (PMID 38673991, 2024). "Presently, eighteen distinct mutations in the LEP gene have been documented as contributors to severe obesity [2,] (Table." (PMID 39041042, 2024). "For example, increased estrogens, insulin resistance, mammary fat inflammation, increased aromatase expression, and elevated leptin levels are all thought to play a role in the pathogenesis of obesity-associated breast cancer." (PMID 38418549, 2024). "Plasma leptin concentration is also directly related to obesity, such that the amount of leptin increases with increases in fat tissue, leading to obesity-associated hyperleptinemia." (PMID 38933888, 2024). "In conclusion, rat models that separately elevate leptin or body weight develop distinct OA-associated phenotypes, revealing how obesity increases OA pathology through both leptin-dependent and independent pathways." (PMID 37457883, 2023). "Metformin treatment for 8 weeks in adolescents with obesity has also been associated with a significant decrease in the level of other key adipokine—leptin." (PMID 37373251, 2023). "LEP gene mutation decreases leptin concentration and increases type 2 diabetes mellitus and obesity." (PMID 37635936, 2023). "Decreased tissue sensitivity to leptin leads to obesity and is closely linked to insulin insensitivity." (PMID 36899958, 2023). "On the other hand, low levels of leptin and high levels of ghrelin are associated with an increased risk of obesity, either by reducing feelings of fullness or by stimulating appetite." (PMID 37576958, 2023). "Previous studies have demonstrated that obesity is associated with leptin resistance and increased leptin levels with a concomitant increase in SOCS-3, involved in signal transduction inhibition of leptin and several cytokines." (PMID 36852336, 2023). "Bi-allelic (homozygous or compound heterozygous) loss-of-function mutations in the genes encoding leptin and the leptin receptor cause hyperphagia, an intense drive to eat and severe obesity in the first year of life." (PMID 37661743, 2023). "For future studies, it would be interesting to look further into which has a bigger effect (adiponectin, leptin, inflammatory markers, or other hormones) in its role of associating dementia with obesity." (PMID 37363537, 2023). "Nevertheless, the dogma that all inflammatory cytokines aggravate obesity and associated comorbidities is questioned by the relationship between leptin and IL-1." (PMID 36674935, 2023). "We observed increased upper respiratory proinflammatory responses associated with obesity in this cohort, an effect that was also mimicked at late timepoints in our mouse model of leptin administration with influenza infection." (PMID 37857661, 2023). "Since serum leptin levels exhibit a direct correlation with body fat mass in individuals with obesity, its role in the development of obesity-linked complications has received a great deal of attention." (PMID 36750692, 2023). "In fact, in zinc deficient-obesity, leptin rise promoted the increase in macrophage infiltration in adipose tissue of mice fed a high-fat diet." (PMID 38260166, 2023). "Studies provided evidence that leptin has been identified as a critical immune modulator in an obesity-associated inflammation by promoting pro-inflammatory immune response." (PMID 38259965, 2023). "We propose that Slug-induced leptin resistance in the hypothalamus is a causal factor for obesity and its associated disorders." (PMID 36512408, 2023). "In animal models, obesity has been linked to the overproduction of adipokines, such as leptin, that contribute to thrombosis." (PMID 37396589, 2023).
Obesity (continued). "Higher BMI was observationally associated with HMB in their study, and leptin and insulin resistance were potential mediators between obesity and female reproductive health." (PMID 37828525, 2023). "Leptin exerts its behavioral and metabolic effects by modulating signaling of AgRP neurons that are susceptible to obesity-induced leptin resistance." (PMID 37043384, 2023). "Leptin is a proinflammatory adipokine that contributes to obesity-associated osteoarthritis (OA), especially in women." (PMID 37457883, 2023). "Genetic causes of obesity can be classified as (A) monogenic causes that result in a single mutation located mainly in the leptin–melanocortin pathway." (PMID 38138997, 2023). "ANGPTL8 showed a strong positive correlation with hsCRP, leptin, and chemerin which are well-known risk factors specifically for obesity, and broadly for metabolic syndrome." (PMID 38189043, 2023). "Obesity is linked to hyperactive adipose tissue with an inflammatory secretory phenotype including leptin and IL-6 that cause, when prolonged, subacute chronic inflammation and insulin resistance." (PMID 36768831, 2023). "In leptin-deficient ob/ob mice, a genetic model of obesity, plasma levels of retinol-binding protein 4 were higher but bisretinoids in retina were not elevated." (PMID 37146972, 2023). "Significantly, we revealed an indispensable role of leptin/obR signaling in regulating M1 macrophage polarization in obesity-associated neutrophilic airway inflammation." (PMID 37488474, 2023). "Obesity is linked to hyperactive adipose tissue that secretes inflammatory adipocytokines, e.g., leptin and interleukin-6 (IL-6), which cause, with prolonged exposure, subacute chronic inflammation and insulin resistance." (PMID 36768831, 2023). "HDACs are crucial in the expression of leptin, a hormone that promotes satiety and can contribute to obesity, which is a major risk factor in the development of CVDs." (PMID 38255639, 2023). "Obesity and aging are associated with impaired insulin-sensitivity, leptin-sensitivity, and nutrient-sensing in neurons within the ARC, which promotes increased food intake, hepatic gluconeogenesis, and adipocyte lipolysis." (PMID 37425648, 2023). "Previous research has consistently demonstrated that a high leptin concentration in obesity is associated with increased cardiovascular risks, behavioral disorders related to food intake, impairment in weight loss, and inflammation." (PMID 38063544, 2023). "In patients only with obesity, elevated serum leptin concentrations lead to increase cardiovascular risk; however, in the context of chronic diseases patients, such as CKD, this situation is not clear." (PMID 36967775, 2023). "Leptin and adiponectin play crucial roles in obesity-associated diseases, and the group that received the dose of 10 μg/mL showed significantly higher levels of adiponectin and leptin than the control group." (PMID 38140369, 2023). "In obesity associated with hyperleptinemia, leptin-induced reactive oxygen species (ROS) generation in vascular tissues is suggested to be a mechanism involved in the physiopathological processes of hypertension and atherosclerosis." (PMID 36978976, 2023). "Overall, obesity is linked to higher risk and progression of MS, influencing relapse rates, brain volume decline, neuroinflammation, hormone levels (leptin and adiponectin), and gut microbiota." (PMID 38026693, 2023). "Diet-induced obesity as well as the leptin-deficient (ob/ob) genetic mouse model of obesity promotes macrophage infiltration in PVAT surrounding abdominal aortas and further increases Ang II-induced AAAs." (PMID 37034348, 2023). "To date, more than 100 different adipokines have been discovered, of which adiponectin and leptin are the most studied to be implicated in obesity-related tumorigenesis and progression." (PMID 37509120, 2023).
Obesity (continued). "Obesity related adipokines like leptin have been linked with several cardiovascular risk factors, but previous results about the association of leptin with arterial stiffness are inconsistent." (PMID 36973671, 2023). "Circulating SIRT1 is negatively associated with fat mass, leptin, and insulin resistance, and positively associated with adiponectin, an “anti-obesity” hormone." (PMID 37679377, 2023). "This review systematically states the relationship between leptin and common risk factors for AS (inflammation, obesity, diabetes mellitus, hypertension, and sleep disorders) and provides some new thoughts on the future direction of research on both." (PMID 37986371, 2023). "This is exemplified by monogenic forms of obesity due to penetrant rare variants affecting the development and/or function of the hypothalamic leptin-melanocortin pathway." (PMID 37586323, 2023). "Poor reproductive status, which is associated with increasing obesity, is postulated to be due to the effect of leptin on the kisspeptin-GnRH pathway." (PMID 38203349, 2023). "Increased leptin levels in obesity are associated with activation of pro-inflammatory signaling and increased thrombosis and arterial distensibility in obese patients." (PMID 37841878, 2023). "Low circulating levels of leptin are a hallmark of obesity and deficiencies in leptin production, transport and signalling are known causes of increased weight." (PMID 36121552, 2023). "Collectively, these data support that α-MSH overexpression fails to reduce normal body weight gain during aging or reverse obesity induced by either HFD or leptin deficiency." (PMID 37069175, 2023). "In order to explore the effect of Y-ASCs transplantation is related to age or degree of obesity, leptin-deficient ob/ob mice were choosed for morbidly obese." (PMID 37533129, 2023). "Macrophages are present in less than 10% of AT in lean mice and humans but can reach up to 40%–50% in individuals with obesity and leptin-deficient rodents with obesity by local proliferation and infiltration." (PMID 37608837, 2023). "Rs6966536 (allele G) of the LEP gene has been implicated in the development of obesity in a South African population." (PMID 36983642, 2023). "Leptin is an adipokine directly correlated with the pro-inflammatory phenotype associated with obesity." (PMID 36839226, 2023). "Leptin also stimulates macrophage proliferation in a dose-dependent manner, meaning obesity-associated hyperleptinemia can increase the proliferation of ATMs." (PMID 37283763, 2023). "Leptin is an obesity-associated adipokine known as the “obesity hormone”, whose circulating levels increase proportionally to body fat mass." (PMID 36835413, 2023). "Obesity is associated with increased levels of adipokines and proinflammatory cytokines, including leptin, tumour necrosis factor alpha (TNF-α) and multiple interleukins (ILs)." (PMID 37686844, 2023). "Initially, the mechanism regarding BBS obesity was shown to involve a reduced hypothalamic response to leptin, which results in hyperphagia, partly caused by nervous system cilium impairment." (PMID 37571382, 2023). "Fecal transplantation from obese, leptin-deficient mice induced obesity in lean mice, emphasizing the great influence of the intestinal microbiome composition on energy metabolism." (PMID 37047584, 2023). "Leptin has garnered considerable interest due to its levels being significantly elevated in obesity and linked with a more proinflammatory state, which has negative effects on MS." (PMID 38026693, 2023). "In the present study, we used the PLS method to identify dietary patterns explaining the following obesity-related markers: body fat, visceral fat, BMI, leptin, adiponectin and to further assess their association with leukocyte telomere length (LTL)." (PMID 37231745, 2023). "While monogenic obesity is rare, it results from gene mutations within the leptin/melanocortin pathway in the hypothalamus." (PMID 37762850, 2023).
Obesity (continued). "Increased expression of leptin is reported to be associated with obesity-asthma phenotype through the activation of the STAT3 signaling pathway." (PMID 37251328, 2023). "Impaired leptin action, referred to as leptin resistance, is an important risk for obesity, and leptin resistance impedes leptin therapy to combat obesity and related metabolic disease." (PMID 36512408, 2023). "Overweight and obesity are associated with increased morbidity and mortality risk of MM through inflammatory cytokines, leptin, insulin, and insulin-like growth factor levels." (PMID 36910611, 2023). "In a linear regression model, we analyzed if rs10487505 influences circulating leptin levels as well as obesity-associated parameters in this cohort and if the SNP is an expression quantitative trait locus (eQTL) for leptin." (PMID 36833305, 2023). "Non-syndromic obesity is caused by mutations or genetic variants in well-known genes directly regulating energy homeostasis mediated by the leptin–melanocortin signaling pathways in the hypothalamus." (PMID 37571382, 2023). "T cell-specific deficiency of leptin signaling alters T cell metabolism and function in obesity but has minimal effects on obesity-associated systemic metabolism." (PMID 37276236, 2023). "Although partial leptin deficiency was reported to reduce food intake and protect mice from diet-induced obesity and metabolic disorders, it should also be noted that plasma leptin levels remained unchanged in WT and Ip3r1FKO mice." (PMID 36894534, 2023). "We searched for associations between BMI (measure of obesity), leptin (measure of adiposity), glucose, C-peptide and ISHOMA (measures of glucose-insulin metabolism) and circulating serum metabolites." (PMID 37029207, 2023). "Serum concentrations of adipokines, leptin, adiponectin, visfatin and resistin and inflammatory markers associated with low-grade inflammation in obesity, CRP, IL-6, sE-selectin, sVCAM, sPECAM and VEGF, were similar in both groups, regardless of CK-18." (PMID 37189422, 2023). "Obesity is associated with leptin, which is directly proportional to body fat stores and acts on certain hypothalamic neurons." (PMID 37635793, 2023). "This obesity was traced back to a homozygous obesity leptin gene with a frame-shift mutation (deletion of G133), synthesizing a truncated protein." (PMID 37762850, 2023). "Monogenic.Mutations in leptin gene lead to obesity.Incidence of insulin resistance.Mild elevation in blood glucose levels." (PMID 36986591, 2023). "In CKD patients, plasma leptin levels have been inversely associated with glomerular filtration rate and directly associated with urinary albumin levels as well as age and obesity markers (BMI and waist circumference)." (PMID 36901837, 2023). "Lepr defect is the purest form of leptin resistance, and it directly causes obesity and insulin resistance." (PMID 36737598, 2023). "Although the Leptin deficient rodent models are widely used in study of metabolic syndrome and obesity, they fail to develop liver injuries as in patients." (PMID 37705071, 2023). "Consistent with this, global Nur77 knockout mice develop obesity associated with increased food intake and decreased energy expenditure and are insensitive to the anorexigenic effects of leptin." (PMID 36670468, 2023). "Among the adipokines, we will further describe the in vitro, in vivo, and clinical data concerning the role of leptin, recognized as one of the most important mediators of obesity-associated cancers." (PMID 37509120, 2023). "In this study, we used untargeted metabolomics to analyse the association of maternal obesity and adiposity (BMI and leptin, respectively) with maternal serum metabolites (outcome)." (PMID 37029207, 2023). "Leptin-recessive mutated mice (Ob/Ob) lack leptin, consequently exhibiting hyper-phagic, obesity, hyper-insulinemia, and hyper-glycemia." (PMID 37571382, 2023).
Obesity (continued). "In agreement with published data, obesity was associated with elevated leptin and decreased adiponectin compared to lean controls." (PMID 37463992, 2023). "Leptin (ob/ob) or leptin receptor (db/db) deficient mice and humans developed pronounced hyperphagia and obesity, suggesting leptin is a key player in the control of feeding and energy balance." (PMID 38027481, 2023). "Due to the high similarity with humans, we generated Leptin-deficient (Leptin−/−) pigs to investigate the mechanisms and clinical trials of obesity and NAFLD caused by Leptin." (PMID 37705071, 2023). "Genes associated with obesity control several metabolic pathways (e.g., leptin and melanocortin) that are known to regulate complex interactions with neural circuits of the central nervous systems (CNS) and affect neurotransmitter and neuropeptide levels." (PMID 37494308, 2023). "The db/db mice have a homozygous mutation of the leptin gene, which is involved in regulating energy balance, leading to hyperphagia, obesity, and diabetes." (PMID 36839816, 2023). "This suggests that leptin replacement counteracts abnormal levels of cerebellar activation in response to food cues associated with obesity." (PMID 36121552, 2023). "The dysregulation of adiponectin and leptin, two of the most abundant adipokines during obesity, is linked to a pro-inflammatory response in CRC." (PMID 36839339, 2023). "First, the ob/ob mice have a mutation in the leptin gene and increase appetite, and progressive food intake leads to the development of severe obesity and fatty livers." (PMID 37558739, 2023). "COBLL1 rs6717858 is associated with plasma leptin levels secreted from adipose tissue and obesity-related factors, such as body mass index (BMI), central obesity, waist circumference (WC), fat mass, and lipid levels (prominent effect in women)." (PMID 36835164, 2023). "Obesity-associated abnormalities in the secretion of adipokines such as leptin and adiponectin by adipose tissue can promote cancer development and lead to the activation of oncogenic intracellular molecular pathways." (PMID 37444627, 2023). "Among these, six metabolites were associated with measures of obesity and adiposity (BMI and leptin) and nine metabolites with parameters of the glucose-insulin axis (glucose, C-peptide, ISHOMA)." (PMID 37029207, 2023). "For acute coronary syndromes, the study found that post-dialytic hypotension, elevated leptin levels/obesity, and anemia of CKD were associated with increased odds of occurrence." (PMID 38034195, 2023). "By obesity, the association of LEP gene rs7799039 GG plus GA genotypes with breast cancer was substantiated in normal-weight women (OR: 0.78, 95% CI: 0.63 to 0.98)." (PMID 37274250, 2023). "Leptin levels increase during the early phase of diet-induced obesity and are linked to NO overproduction and protection against endothelial dysfunction." (PMID 37190105, 2023). "Some studies revealed that the TNBC is also associated with weight gain (obesity), which in turn is associated with the excess secretion of adipokine protein, named Leptin (16kDa), by the adipocytes in response to obesity-related stimuli." (PMID 37174125, 2023). "In obesity, increased leptin and adipocytes are associated with an imbalance between pro and anti-inflammatory cytokines." (PMID 37090773, 2023). "Previous studies have observed the role of obesity in promoting cancer growth, as it causes chronic inflammation and promotes cell proliferation through the secretion of leptin from adipose tissue." (PMID 36771423, 2023). "The obesity-regulated gene LEP encodes the hormone leptin that besides regulating appetite and body mass plays a role in proinflammatory immune response, angiogenesis and lipolysis." (PMID 37237325, 2023). "In obesity and associated metabolic diseases, a decreased plasma concentration of adiponectin along with increased leptin levels have been found." (PMID 37049592, 2023).